RN7SL67P (RNA, 7SL, cytoplasmic 67, pseudogene)
Gene: Miscellaneous RNA gene on chromosome 12 (19,303,480 to 19,303,775, forward strand). Ensembl gene ENSG00000243854.
Homologues: Orthologues: chimpanzee Metazoa_SRP (93% identical), macaque Metazoa_SRP (86% identical), rabbit Metazoa_SRP (66% identical). Paralogues in human: RN7SL1 (83% identical), RN7SL2 (82% identical), RN7SL3 (82% identical), RN7SL664P (81% identical), RN7SL230P (80% identical), RN7SL481P (80% identical), RN7SL45P (79% identical), RN7SL118P (79% identical), RN7SL383P (78% identical), RN7SL448P (78% identical), Metazoa_SRP (78% identical), RN7SL769P (78% identical), and 702 more.